OTP (orthopedia homeobox)
Description:
Probably involved in the differentiation of hypothalamic neuroendocrine cells.
Tractability: No criterion of Open Targets' tractability assessment is met for any kind of drug.
Gene: Protein-coding gene on chromosome 5 (77,628,712 to 77,638,713, reverse strand). Ensembl gene ENSG00000171540.
Subcellular location: Nucleus
Subcellular location (Human Protein Atlas): Nucleoplasm; Nuclear bodies; Nucleoli fibrillar center
Gene Ontology:
Molecular function: DNA-binding transcription repressor activity, RNA polymerase II-specific; protein binding; RNA polymerase II transcription regulatory region sequence-specific DNA binding; DNA binding; DNA-binding transcription factor activity, RNA polymerase II-specific
Biological process: negative regulation of transcription by RNA polymerase II; neuron differentiation; regulation of DNA-templated transcription
Cellular component: chromatin; nucleus
Genetic constraint (gnomAD): Loss-of-function variants: 5 observed, 14.47 expected, observed/expected ratio (o/e) 0.35, 90% interval 0.18 to 0.73. The synonymous counts are far from expectation, so gnomAD's model fits this gene poorly and the ratio says little. Missense variants: 428 observed, 374.71 expected, observed/expected ratio (o/e) 1.14, 90% interval 1.05 to 1.24. Synonymous variants: 229 observed, 175.8 expected, observed/expected ratio (o/e) 1.3, 90% interval 1.17 to 1.45.
Homologues: Orthologues: chimpanzee OTP (100% identical), macaque OTP (100% identical), mouse Otp (100% identical), pig OTP (100% identical), rat Otp (100% identical), dog OTP (99% identical), guinea pig OTP (99% identical), tropical clawed frog OTP (87% identical), zebrafish otpa (85% identical), zebrafish otpb (82% identical). Paralogues in human: ARX (30% identical), RAX (27% identical), PAX7 (25% identical), SHOX2 (25% identical), PITX1 (25% identical), PITX2 (25% identical), PAX3 (24% identical), ALX4 (24% identical), SHOX (24% identical), VSX2 (23% identical), OTX1 (23% identical), UNCX (23% identical), and 38 more.
Diseases named in the same sentence as OTP in open-access papers:
OTP is named in the same sentence as 20 diseases in open-access papers, as found by Europe PMC text mining. Sharing a sentence is not in itself a finding about the gene and the disease. The quoted sentences say what the papers report.
lung carcinoids (7 papers, 2018 to 2025). "We provide a comprehensive overview of available literature demonstrating OTP as a promising, highly sensitive, and specific marker for pulmonary carcinoid tumors with a favourable prognosis." (PMID 31597385, 2019). "Although OTP has frequently been described as a key player in the development of the hypothalamic neuroendocrine system of vertebrates, its function in lung carcinoids remains to be elucidated." (PMID 31597385, 2019). "Orthopedia homeobox (OTP) was used as a potential marker for lung carcinoids in humans." (PMID 35274020, 2022). "Only recently, OTP has been found to be a highly specific marker for pulmonary carcinoid tumors." (PMID 30257451, 2018). "Interestingly, we found that OTP is highly expressed in these speculated lung carcinoid precursors." (PMID 31597385, 2019). "There were no cases with TTF-1-positive and OTP-negative phenotype in this series; however, we have experienced two recurrent/metastatic lung carcinoid tumors with TTF-1-positive and OTP-negative phenotype, which were not included in this series." (PMID 29770932, 2018).
Pulmonary Neuroendocrine Tumors (5 papers, 2019 to 2025). "The OTP gene from humans was cloned some time ago, but only during the last few years, it could be shown that OTP has a high diagnostic value concerning pulmonary neuroendocrine tumours." (PMID 33213520, 2020). "Here, we comprehensively review current literature on OTP function, OTP expression in lung neuroendocrine neoplasms, and possible molecular pathways through which it might operate in both normal and pulmonary neuroendocrine tumor tissue." (PMID 31597385, 2019). "Recent studies have shown that pulmonary neuroendocrine tumor (NET) subgroups, defined by the transcription factors OTP and ASCL1, correlate with age, sex, and tumor location." (PMID 41196447, 2025). "Emerging molecular markers, such as protein expression of CD44, ASCL1, and OTP and TERT gene expression have shown prognostic value in lung NETs, alongside traditional markers like Ki-67 and somatostatin receptors." (PMID 40026252, 2025).
carcinoids (4 papers, 2019 to 2022). "Atypical carcinoids with proliferation index ≥5% and loss of OTP and/or CD44 were at high risk for distant metastases." (PMID 35805004, 2022). "In this series of 171 carcinoids, we could show that loss of OTP and CD44 expression was strongly associated with unfavorable disease outcome." (PMID 35805004, 2022). "In contrast, patients who presented with disseminated disease at baseline or developed metastases during follow-up could be identified by atypical carcinoid morphology in combination with a high proliferation index (Ki-67 ≥ 5%) and loss of OTP and/or CD44 expression." (PMID 35805004, 2022). "In more recent study by Papaxionis and colleagues, CD44 and OTP were incorporated with carcinoid gradation in a multivariate model with similar results." (PMID 35805004, 2022). "After radical surgical resection, however, extensive follow-up may be futile in case of a carcinoid with a favorable biomarker profile (low mitotic count, low Ki-67 expression, and normal OTP/CD44 expression), which was 47% in our cohort." (PMID 35805004, 2022). "We identify therapeutically relevant molecular groups of pulmonary carcinoids, suggesting DLL3 and the immune system as candidate therapeutic targets; we confirm the value of OTP expression levels for the prognosis and diagnosis of these diseases, and we unveil the group of supra-carcinoids." (PMID 31431620, 2019). "Moreover, OTP is a highly specific marker for carcinoids of pulmonary origin and recent genome wide analysis has identified OTP as a crucial predictor of aggressive tumor behaviour." (PMID 31597385, 2019). "In addition, it was suggested that the genes OTP/CD44 might play an important role in carcinoid development." (PMID 31597385, 2019). "This study confirmed that adding OTP, CD44, and Ki-67 to the carcinoid classification improved the identification of patients who are at risk for metastatic disease." (PMID 35805004, 2022). "Patients (n = 76) with carcinoids harboring a favorable marker profile (Ki-67 < 5%, mitotic count < 2 per 2 mm2, and OTP or CD44 positivity) exclusively did not develop distant metastases during follow-up." (PMID 35805004, 2022). "Carcinoid tumors showed a positive OTP messenger-RNA (mRNA) expression whereas normal tissues, high-grade neuroendocrine carcinomas, and the evaluated NE cell lines did not express OTP mRNA." (PMID 31597385, 2019).
glioma (4 papers, 2018 to 2025). A benign or malignant brain and spinal cord tumor that arises from glial cells (astrocytes, oligodendrocytes, ependymal cells). "HOXC6, WT1, CD70, and OTP expression was upregulated in glioma tissues from patients with high-risk scores." (PMID 38499392, 2024). "Based on multivariate Cox regression analysis, the immune signature created using HOXC6, WT1, CD70, and OTP represented an independent prognostic factor for glioma patients with TERTp mutations." (PMID 38499392, 2024). "HOXC6, WT1, CD70, and OTP expression was elevated in glioma tissues from high-risk score patients carrying wild-type TERTp." (PMID 38499392, 2024). "HOXC6, WT1, CD70, and OTP were highly expressed in high-risk vs. low-risk glioma samples." (PMID 38499392, 2024). "In conclusion, an immune signature based on HOXC6, WT1, CD70, and OTP expression was shown to serve as an independent and specific prognostic indicator for patients with TERTp- mutant gliomas." (PMID 38499392, 2024). "As for both LYVE1 and OTP, to our knowledge this study presents the first evidence of hypoxia-related regulation and clinical correlation in IDH1mut glioma patients." (PMID 30257451, 2018). "Focusing on the TERTp-mutant glioma subtype, we developed an immune-related gene signature including HOXC6, WT1, CD70, and OTP that showed significant prognostic value for TERTp-mutant gliomas, but not for TERTp wild-type gliomas, in two TCGA cohorts." (PMID 38499392, 2024). "Among the seven key genes (HOXD11, HOXC9, HOXC6, HOXA3, FBXO39, OTP, and HMGA2) consistently detectable in both normal astrocyte cell lines (SVG-P12) and glioma cell lines (U87, U251, LN229), tumor cell lines exhibited significantly upregulated expression compared to normal cell lines." (PMID 41049291, 2025).
metastatic disease (3 papers, 2022 to 2025). "Based on our results, the absence of nuclear OTP expression is associated with AC subtype, metastatic disease, and adverse disease outcome." (PMID 38896236, 2025). "Our results confirm this for the OTP since absence of OTP expression was associated with metastatic disease and shorter DSS." (PMID 38896236, 2025). "In a univariable Cox regression model, absence of OTP expression was associated with adverse outcome along with atypical histological subtype, metastatic disease, Ki-67 proliferation index > 1%, and larger tumour size." (PMID 38896236, 2025).
asthma (1 paper, 2018). "Several studies showed that NOS1 gene polymorphism was associated with asthma, OTP played an essential role in the specification of neuronal cell lineages in the developing hypothalamus and NANOS1 was required for maintaining oocyte production." (PMID 29416711, 2018).
glioblastoma (1 paper, 2025). The most malignant astrocytic tumor (WHO grade IV). "To investigate the biological relevance of candidate transcription factors enriched in the NSC-like compartment, we next performed functional validation of OTP, C1QL2, and VAX2 using the LN229 glioblastoma cell line (ATCC, CRL-2611)." (PMID 41378293, 2025).
lung carcinoma (1 paper, 2024). "OTP was identified as a reliable prognostic indicator in lung carcinomas, including neuroendocrine ones." (PMID 38499392, 2024).
neuroendocrine carcinoma (1 paper, 2019). A malignant neuroendocrine neoplasm composed of cells containing secretory granules that stain positive for NSE and chromogranin. "According to the results, neither non-neuroendocrine tumors nor high grade neuroendocrine carcinomas stained positive for OTP." (PMID 31597385, 2019).
neuroendocrine tumors (1 paper, 2019). "OTP expression in other neuroendocrine tumors and/or normal tissue and organs has been investigated in six studies." (PMID 31597385, 2019).
Obesity (1 paper, 2017). Accumulation of substantial excess body fat. "Further inspection of OTP in an additional 935 GOOS cases identified 4 additional rare heterozygous missense variants, altogether detecting 8 variants in OTP in our severe obesity cohort." (PMID 29107289, 2017). "We sequenced OTP in 2548 people with severe early-onset obesity and found a rare heterozygous loss of function variant in the homeodomain (Q153R) in a patient who also had features of attention deficit disorder." (PMID 29107289, 2017). "Given the small number of variants identified and the limited clinical information we have on OTP variant carriers, additional replication will be required to investigate the potential contribution of these variants to obesity." (PMID 29107289, 2017). "In contrast to SIM1, there have been no reports to date of obesity associated with OTP mutations or haploinsufficiency." (PMID 29107289, 2017).
pancreatic NET (1 paper, 2019). "Moreover, neither SCLC nor any pancreatic NET expressed OTP." (PMID 31597385, 2019).
small cell lung carcinoma (1 paper, 2025). Small cell lung cancer (SCLC) is a highly aggressive malignant neoplasm, accounting for 10-15% of lung cancer cases, characterized byrapid growth, and early metastasis. "OTP is consistently expressed in TCs and in a subset of ACs, particularly those of peripheral origin, but is absent in small cell lung cancers (SCLCs), large cell neuroendocrine carcinomas (LCNECs), and non-pulmonary NETs." (PMID 41196447, 2025).
tumor (8 papers, 2018 to 2025). "We investigated the association of OTP expression with clinical parameters in series of 164 PC tumour patients." (PMID 38896236, 2025). "The aim of our study was to evaluate the association of OTP expression with disease progression and disease-specific survival in PC tumour patients." (PMID 38896236, 2025). "Thus, OTP immunohistochemistry should be used in PC tumour diagnostics; it identifies patients at risk for tumour relapse who would need an intensified follow-up." (PMID 38896236, 2025). "OTP expression has been shown to be associated with different levels of DNA methylation in PCs, suggesting a possible mechanism by which OTP expression affects the behaviour of these tumours." (PMID 38896236, 2025). "Loss of OTP has also been linked to decreased CD44 expression, a cell adhesion molecule involved in tumor suppression and differentiation." (PMID 41196447, 2025). "It has been demonstrated that combining ASCL1 with markers such as OTP, HNF1A or CD44 improves NETs subclassification, with identifying groups linked to clinical characteristics, including patient sex and tumor location." (PMID 41196447, 2025). "With all three antibodies, 80–84% of TC tumours expressed OTP, while only 51–68% of AC tumours showed OTP expression." (PMID 38896236, 2025). "First, their study included 110 PC tumours that were classified into five different groups according to OTP staining intensity (0- + 4)." (PMID 38896236, 2025). "Univariate analysis showed that Ki-67, mitotic index, OTP, CD44, and tumor diameter were associated with development of distant metastases." (PMID 35805004, 2022). "In this study, we revealed several pivotal regulatory TFs (HOXC5, ISL1, VENTX, and OTP) in tumor cells by integrating scRNA-seq and scATAC-seq data and further experimentally validated their roles in tumor growth." (PMID 35853872, 2022). "Moreover, based on our findings, OTP expression cannot be reliably used to differentiate between TC and AC tumours." (PMID 38896236, 2025). "In addition, relatively large intensity differences between the OTP clones were detected in some individual tumours." (PMID 38896236, 2025). "Localization analysis of HOXD11 and OTP—selected for high expression abundance and consistency with in vitro validation—revealed predominant tumor-specific localization in paired tumor-adjacent samples (n = 2), while showing diffuse distribution in tumor-only samples (n = 2)." (PMID 41049291, 2025). "Immunohistochemical staining with three different primary OTP antibodies (OTP pAb, CL11222, and CL11225) was performed on a total of 164 primary PC tumour samples." (PMID 38896236, 2025). "In conclusion, integrating OTP and ASCL1 refines pulmonary NET classification into four histologically and biologically distinct subgroups, providing additional insight into tumor heterogeneity." (PMID 41196447, 2025). "Through immunohistochemical analysis, TC tumours were considered significantly more frequently as positive for all OTP clones (OTP pAb, CL11222, and CL11225) than AC tumours (p = 0.043, p < 0.001, and p = 0.007, respectively)." (PMID 38896236, 2025). "In the current version of the WHO classification, co-expression of nuclear OTP and CD44 is a prognostic factor for PC tumour patients." (PMID 38896236, 2025). "We identified tumor cell-specific regulatory programs mediated by four key transcription factors (TFs) (HOXC5, VENTX, ISL1, and OTP), and these TFs have prognostic significance in The Cancer Genome Atlas (TCGA) database." (PMID 35853872, 2022). "The risk of developing distant metastases based on histopathological characteristics (Ki-67, p16, Rb, OTP, CD44, and tumor diameter) was evaluated using multivariate regression analysis and the Kaplan–Meier method." (PMID 35805004, 2022).
tumor (continued). "Univariate analysis demonstrated that tumor diameter (p < 0.001), CD44 (p < 0.001), OTP (p < 0.001), mitotic count (p < 0.001), and Ki-67 (p < 0.001) were significantly associated with distant metastases at follow-up." (PMID 35805004, 2022). "Concordant OTP and ASCL1 expression profiles were observed in all tumor tissues from each patient." (PMID 41196447, 2025). "Based on our findings, the immunohistochemical staining patterns with OTP antibodies were mostly homogeneous for those tumour samples that were clearly positive or negative." (PMID 38896236, 2025). "OTP is also a highly specific pulmonary NET marker, rarely expressed in other tumor types." (PMID 41196447, 2025). "While immunohistochemical OTP status cannot be used for subtyping PC tumours reliably, the absence of OTP expression is a strong indicator for aggressive disease progression and shorter disease-specific survival in PC tumour patients." (PMID 38896236, 2025). "O + /A + tumors showed solid-spindle features and diffuse GRP and frequent ACTH expression, trabecular patterns characterized ASCL1-negative tumors, while oncocytic histology predominated in OTP-negative tumors, highlighting their role in defining tumor heterogeneity." (PMID 41196447, 2025). "These cases suggest the existence of TTF-1-positive and OTP-negative phenotype, which might be related to TTF-1/OTP double-positive biologic group with subsequent loss of OTP due to tumor progression." (PMID 29770932, 2018).
OTP also shares sentences with these, for which no sentence is quoted: Anxiety (1 paper); autism (1); cancer (1); gastric cancer (1); kidney cancer (1); Parkinson disease (1).